CXCR2 (C-X-C motif chemokine receptor 2)
Diseases named in the same sentence as CXCR2 in open-access papers (continued):
Sharing a sentence is not in itself a finding about the gene and the disease.
tumor (continued). "Next, we clarified the role of CCR2 and CXCR2 antagonists in the TACE-induced inhibition of tumor growth." (PMID 36403057, 2022). "Meanwhile, the CXCL1/CXCR2 signaling pathway was also thought to play important roles in regulating tumor growth and promoting tumor metastasis." (PMID 36117156, 2022). "Genetic ablation of CXCR2 resulted in lower neutrophil infiltration and suppression of tumor growth." (PMID 33603130, 2022). "Knockdown of SMAD4 from human CRC cells enhances CXCL1 and CXCL8 expression and accumulates CXCR2+ neutrophils to CRC tumor." (PMID 35935996, 2022). "In contrast, the same overall dose of cytotoxic agents administered as an MC regimen prevented therapy-induced CXCR2 paracrine signaling, thus enhancing treatment response and extending the survival of tumor-bearing mice." (PMID 35628979, 2022). "CXCR2 antagonists have been reported to make MDSCs range from overt infiltration to subtle infiltration and T-cell infiltration increase in the tumor sites." (PMID 36246629, 2022). "The modulation of CXCR2 expression on T cells has been shown to increase treatment efficacy in a range of tumour models due to the enhancement of T cell trafficking." (PMID 35205725, 2022). "A strategy to exploit the expression of pro-tumoural cytokines is to ectopically express their receptors, such as CXCR2 on desired effector cells, thereby targeting them to the tumour." (PMID 35205725, 2022). "For example, a decrease in its expression in hepatocellular carcinoma was found to increase CXCR2 expression, which then leads to the increased migration of tumor cells." (PMID 35216283, 2022). "Specifically, we found that chemotherapy induces the expression of neutrophil chemoattractants in tumour cells and subsequent recruitment and infiltration of Gas6 expressing neutrophils to the liver in a CXCR2-dependent manner." (PMID 35022267, 2022). "Distracting with the oxysterol-CXCR2 pathway delayed the tumor growth and prolonged the overall survival in the tumor-bearing mice model." (PMID 35585567, 2022). "The myeloid cells in the RM-1 tumor xenografts expressed Cxcr2, the Cxcl5 receptor, at the highest level." (PMID 36369237, 2022). "As a member of the CXC chemokine family, CXCL5 is the ligand of CXCR2 and is not only derived from primary tumor cells but is also secreted by immune cells in the TME." (PMID 35246503, 2022). "The role of CXCR2 and its ligands in neutrophil activation and maturation in the tumor context is still discussed." (PMID 35158948, 2022). "In this study, CXCR2+ cells were enriched in stroma‐dense primary and secondary tumours in the second cohort of matched colorectal primary tumours and liver metastases." (PMID 35879507, 2022). "There is extensive evidence to indicate that the CCL2/CCR2 and CXCLs/CXCR2 axes can stimulate tumor growth and angiogenesis, and promote the infiltration and activation of host immune cells." (PMID 36403057, 2022). "Other cells that are recruited to the tumor niche via CXCR2 include granulocytic myeloid-derived suppressor cells (MDSCs), regulatory T cells (Treg), and bone marrow-derived mesenchymal cells (BM-MCs)." (PMID 35216283, 2022). "CXCR2-inhibition induces reprogramming of the tumour immune microenvironment that promotes ICI in NASH-HCC." (PMID 35477863, 2022). "Cancer cells trigger NETosis by CXCR1 and CXCR2 activation; NETs protect tumor cells from contact with cytotoxic T cells and NK cells, promoting cancer cell dissemination and lung metastasis." (PMID 35574410, 2022). "CXCR2 expression was also assessed in a second cohort of unique CRC primary tumours and synchronously resected matched liver metastases." (PMID 35879507, 2022).
tumor (continued). "Using neutrophil–tumor co-cultures, researchers have demonstrated that upregulation of CXCR2 increases the recruitment of TANs to enable the formation of neutrophil extracellular traps (NETs) in response to pro-inflammatory stimuli." (PMID 35884845, 2022). "In animal studies of bladder, renal cell, and CRCs, CXCL5 secreted by tumor cells binds its receptor CXCR2 and activates the downstream AKT/NF‐κB signaling pathway, thereby stimulating the proliferation and aggregation of endothelial cells." (PMID 35702353, 2022). "CXCR2 is a chemokine receptor expressed in different types of cells including leukocytes, tumor cells, endothelial cells, chondrocytes, and mesenchymal cells." (PMID 35755815, 2022). "IL-8 is a ligand for CXCR2 that is secreted by several cancer types and the activation of NF-kB, mediated by IL-8, promotes the switch to a pro-tumor neutrophil profile." (PMID 36295558, 2022). "Although the levels of CXCR2-expressing neutrophils is correlated to high grade breast cancers, its role is rather to counteract tumor progression, as it is correlated with a better survival of the patients and its deletion favors tumor growth and metastasis." (PMID 36588678, 2022). "Upon activating the membrane G-protein-coupled receptor CXCR2, tumor oxysterols recruit neutrophils to promote an immunosuppressive milieu within the tumor microenvironment." (PMID 35455931, 2022). "CXCR2 converges information from tumor cells and the microenvironment, leading to disease progression, chemoresistance, and immunosuppression, supporting a role for the CXCR2 receptor as a novel therapeutic target." (PMID 35517812, 2022). "Analysis of the GSE6919 dataset indicated that CXCR2 expression in metastatic tumor tissue was higher than that in primary tumor tissue, which further confirmed our results." (PMID 35853880, 2022). "This combination resulted in compensatory recruitment into the tumor of neutrophil populations highly expressing CXCR2." (PMID 35664746, 2022). "They reported that TGF-βR deletion caused an increase in CXCR2 signaling, which led to increased MDSC recruitment into the tumor microenvironment." (PMID 35517812, 2022). "Expectedly, deltarasin treatment statistically and biologically significantly inhibited LLC tumor growth in WT, Cxcr1−/−, and Cxcr2+/− mice." (PMID 35327394, 2022). "To further examine the concept that CXCR2 antagonism sensitises NASH-HCC to anti-PD1 therapy we asked if combination therapy activates classic T-cell mediated anti-tumour immunity." (PMID 35477863, 2022). "In other reports, CXCL2 dose-dependently increases the expression of VEGF within the angiogenic front of tumor margins, thereby promoting tumor angiogenesis, tumor growth and hepatic metastasis in the CXCR2-expressing CT26 CRC cell-induced CRC mice." (PMID 35954156, 2022). "Blockade of CCL2/CCR2 and CXCLs/CXCR2 enhanced the anti-tumor effect of TACE treatment in this model." (PMID 36403057, 2022). "Cancer-cell-produced agonists to CXCR2 are widely involved in neutrophil recruitment to the tumor microenvironment." (PMID 36555469, 2022). "The activation of CXCL2 and its associated receptor CXCR2 by KRAS signaling is thought to suppress immune response and promote tumor proliferation." (PMID 36033462, 2022). "It has been also shown that PCa-derived CXCL5 can recruit CXCR2-expressing MDSCs in a mouse model of PCa and inhibition of MDSCs through blocking of CXCL5-CXCR2 axis can restore anti-tumor activities." (PMID 36338516, 2022). "Given that CXCR2 is almost exclusively expressed on neutrophils, we were curious as to their role in AZD5069/anti-PD1 therapy and its associated tumour immune cell remodelling." (PMID 35477863, 2022). "An ongoing phase I/II trial aimed at treating metastatic melanoma patients with tumour-infiltrating lymphocytes transduced with CXCR2, followed by high dose IL-2 has clinical outcome reports pending (NCT01740557)." (PMID 35205725, 2022).
tumor (continued). "The CXCL5/CXCR2 signaling axis can also indirectly promote tumor progression via modulating the function of various immune cells within the TME." (PMID 35702353, 2022). "This therapy works through the use of SX-682, a small-molecule inhibitor of CXCR1 and CXCR2, which retards tumor development." (PMID 36060811, 2022). "Pancreas-specific deletion of Cxcr2 in KC mice prevents oncogene-induced senescence, increases tumor proliferation, and decreases survival (Pdx1-Cre; lox-stop-lox-KrasG12D/+; Cxcr2lox/lox)." (PMID 35159011, 2022). "Gold standard therapy temozolomide (TMZ) is known to induce upregulation of IL8/CXCL2/CXCR2 signaling that promotes tumor progression and angiogenesis." (PMID 34681839, 2021). "Targeting CXCR2 obviously inhibited tumor growth, with decreased infiltration of TANs and increased response of T cells." (PMID 33814009, 2021). "CXCR2 was found to be significantly elevated in livers from the CCA orthotopic tumor model compared to control animals (p < 0.0001)." (PMID 34831316, 2021). "Both liver tumor tissue, as well as tumor draining LN, showed a significantly increased expression of CXCR2 and CXCL5 compared to the normal liver and naïve LNs from the control animals." (PMID 34831316, 2021). "This elevation in CXCR4 expression of neutrophils in tumor-bearing animals was almost completely abolished on antibody blockade of the aging-promoting chemokine receptor CXCR2." (PMID 34876407, 2021). "The AUC for CXCL8 (0.8552, p < 0.001) was higher than the AUC for its receptor CXCR2 (AUC = 0.7773, p < 0.001) and classical tumor markers (CEA—AUC = 0.5159 and CA19-9—AUC = 0.6606), and also higher than the AUC for CRP levels (AUC = 0.8488, p < 0.001)." (PMID 34680333, 2021). "For example, a non-canonical Wnt ligand-YAP signaling axis regulated the recruitment of PMN-MDSCs to the tumor bed by promoting the expression of CXCR2-dependent chemokines CCL5 in response to PD-1 blockade." (PMID 35003065, 2021). "We verified that these changes correlated with an increased flux of PMN-MDSCs into tumors, a process that was reversed by tumor-directed genetic silencing of CXCL5 as well as small molecule inhibition of CXCR2." (PMID 34638239, 2021). "Current inhibitors of CXCR is well discussed, and CXCR2 antagonists have been initially considered administrated in respiratory diseases and gradually in cancer for more insights into tumor microenvironment." (PMID 34025668, 2021). "The CXCL1/CXCR2 axis promotes oncogene-induced senescence through NF-κB signalling to restrain tumor growth." (PMID 34575965, 2021). "The binding of CXCR2 and IL-8 can promote a series of tumor cell activities including proliferation, angiogenesis, and invasion." (PMID 34238119, 2021). "Driving effector cells such as NK cells and T cells to express CXCR2 is a novel strategy for increasing the infiltration of anti-tumor immune cells to the TME." (PMID 34944914, 2021). "The serum concentrations of both CXCL8 and CXCR2 were found to be elevated in EC patients, suggesting the significance of CXCL8 as a potential diagnostic tumor marker in EC." (PMID 33390169, 2021). "Collectively, these results revealed that recruitment of neutrophils with immune-suppressive phenotype to tumor microenvironment was mediated by CXCLs/CXCR2 axis and SB225002." (PMID 33814009, 2021). "A CRISPR/Cas9 mediated knockout of CXCR2 in MDA-MB-231 cell lines led to a significant decrease in tumor cell proliferation and migration, compared to the wild-type TNBC cell line." (PMID 34066014, 2021). "The migration of neutrophils to tumors is mainly mediated by CXC chemokine binding to CXCR1 and CXCR2, which can promote tumor growth, invasion, angiogenesis, and metastasis." (PMID 34604045, 2021). "The expression of chemokines such as CXCL8 and its receptor CXCR2 increase as the tumour transitions from the radial to the vertical growth phase." (PMID 34830780, 2021).
tumor (continued). "As immunotherapies gain approval for a wider array of clinical indications, it will become even more important to understand the efficacy of CXCR2 inhibition in combating immunotherapy resistance at different stages of tumor progression." (PMID 34944914, 2021). "Modified CAR inducing the expression of IL-8 receptors, CXCR1 or CXCR2, showed enhanced migration and persistence of T cells in the tumor." (PMID 35008832, 2021). "The chemotaxis of CXCLs/CXCR2 axis was enhanced by tumor stimulation, and we established a co-culture system with Transwell membranes (3 μm)." (PMID 33814009, 2021). "In vivo treatment with danirixin (antagonists of CXCR2) promoted tumor progression in animal models established with CT26 cells." (PMID 34025668, 2021). "Here, we investigated how the adipocyte-specific CXCR2 conditional knockout (cKO) affected the peritoneal tumor microenvironment of OC in a high-fat diet (HFD)-induced obese mouse model." (PMID 34638514, 2021). "We show here that the knock-down of Cxcr2 in PyMT animals led to an increased growth of the primary tumor and lung metastasis." (PMID 34070438, 2021). "The binding of CXCR2 and chemokine induces proliferation, angiogenesis, and invasion of tumor cells." (PMID 34692853, 2021). "Many researchers found that selected chemokines such as CXCL8 and its specific receptor CXCR2 are involved in cancer progression via the stimulation of tumor invasion, angiogenesis and metastasis." (PMID 34680333, 2021). "Although the pharmacological intervention against CXCR2 has shown promising therapeutic benefits, some studies suggest that CXCR2 can potentially play a stage-dependent suppressive role in tumor development." (PMID 34575965, 2021). "Counteracting uncoupled biological aging of circulating neutrophils by blocking the chemokine receptor CXCR2 effectively suppressed tumor growth." (PMID 34876407, 2021). "NPC patients with high CXCR2 expression levels in tumor cells or in stromal cells had shorter overall survival than patients with low CXCR2 levels (P < 0.05)." (PMID 34124076, 2021). "In spontaeous tumor mouse models, inhibition of CXCR2 reduces the infiltration of Ly6G+ neutrophils and tumor formation." (PMID 34359674, 2021). "IL-8 is also related to tumours and inflammation as a C-X-C motif chemokine receptor 2(CXCR2) ligand." (PMID 34776511, 2021). "Herein, this study evaluated the expression of CXCR2 in diverse tumor tissues and matched normal tissues." (PMID 34840630, 2021). "The CXCR1 and CXCR2 inhibitor Reparixin was also able to improve tumor cell apoptosis and decrease tumor volume in a gastric cancer model, when in combination with 5-fluorouracil." (PMID 34575965, 2021). "The different behaviors of reparixin or danirixin depend on the specific target, such as targeting CXCL8, CXCR1/CXCR2 or CXCR2, or depend on the specific target cells, such as tumor cells or different immune cell subpopulations." (PMID 34025668, 2021). "Investigation of the role of CXCR2 on OC tumor growth (TG) and angiogenesis was assessed by the chicken embryo chorioallantoic membrane (CAM) method." (PMID 34038868, 2021). "Tumor‐secreted CXCL1 stimulated the formation of iCAF through CXCR2/pSTAT3, which was blocked by a CXCR2 inhibitor (SB225002)." (PMID 34218518, 2021). "Inversely, the average expression of L-selectin/CD62L and CXCR2 on total circulating neutrophils was significantly diminished in tumor-bearing mice compared with controls." (PMID 34876407, 2021). "Signaling of CXCR2 and its ligands (CXCL8 and CXCL1) leads to the recruitment of tumor-promoting immune cells, such as tumor-associated macrophages and MDSCs." (PMID 34944871, 2021). "On the contrary, the CXCR2 cKO mice had a higher correlation between the tumor weights and ascites (R2 = 0.50) than between the tumor and spleen weights (R2 = 0.01)." (PMID 34638514, 2021).
tumor (continued). "Accordingly, combination targeting of both CCR2+ TAMs and CXCR2+ TANs further augmented the anti-tumor immunity and enhanced the efficacy of chemotherapy in PDA." (PMID 34290984, 2021). "MDSC was reported to participant in tumor metastatic in a pre-metastatic niche pattern, in which MDSC can attract tumor cells via CXCL5/CXCR2 interaction." (PMID 34689842, 2021). "Myeloid-derived suppressor cells (MDSCs) are associated with poor responses to immunotherapy, and the chemokine receptor, CXCR2, is involved in recruiting MDSCs to the tumor." (PMID 34944914, 2021). "Both GROa and IL-8 bind to their canonical receptor CXCR2, expressed on various immune, endothelial, and tumor cells, as well as MSCs." (PMID 33401590, 2021). "Deficiency or inhibition of CXCR2, the main chemokine receptor recruiting MDSCs to TME, reduces the infiltration of CD11b+Ly6Ghigh MDSCs to TME, leading to enhanced anti-tumor effects upon treatment with checkpoint inhibitor." (PMID 34359674, 2021). "CXCL5 recruits neutrophils into the TME, and the CXCL5/CXCR2 axis contributes to tumor growth and metastasis through the activation of PI3K/AKT/GSK-3β/Snail signaling to promote EMT." (PMID 34237033, 2021). "In contrast, knockdown of CXCR2 in the PyMT breast cancer model rendered neutrophils with characteristics in favor of tumor progression." (PMID 34503058, 2021). "Conversely, RNA expression levels of CXCR2, whose gene product expression decreases during neutrophil aging on the surface of these immune cells, were slightly attenuated in advanced tumor stages." (PMID 34876407, 2021). "Overall, we found expression of VEGF and the alternative proangiogenic factors CXCL2 and IL8 in human GBM samples, supporting our findings about the importance of the CXCR2 signaling pathway for tumor progression." (PMID 33807899, 2021). "CXCR2 is dominantly expressed on TAMs, and plays a role in tumor progression through paracrine manner." (PMID 34108959, 2021). "A combined blockage of CCR2 and CXCR2 in a murine PDAC model prevented both CCR2+ macrophages and CXCR2+ neutrophils from entering the tumor, which led to an improved anti-tumor immunity and response to chemotherapy." (PMID 34203869, 2021). "In previous experiment, the expression of CXCR2 both on tumor cells and in tumor stroma was noticed by IHC analysis." (PMID 33814009, 2021). "Consistently, as ascites in ob/ob mice had higher levels of Mφ than lean mice, the HFD-fed CXCR2 WT mice demonstrated dominant floating tumor burdens and tumor-attached Mo/Mφ in OC-induced ascites." (PMID 34638514, 2021). "The results of this study highlighted the changes of tumor microenvironment following chemotherapy or administration of CXCR2 inhibitor." (PMID 33814009, 2021). "Snail knockdown in mouse OvCa cells reduces the expression of the CXCL1/CXCL2 chemokines, which attract MDSCs to the tumor via CXCR2." (PMID 34248988, 2021). "Emerging evidence suggests that CXCR2 is involved in the recruitment of immune cells as well as promotes angiogenesis, tumor growth, and metastases." (PMID 34840630, 2021). "The chemotaxis of neutrophils from peripheral blood to tumor microenvironment is based on CXCLs/CXCR2." (PMID 33814009, 2021). "Resistance to immunotherapy can occur via tumor cell-extrinsic and/or tumor cell-intrinsic mechanisms, and targeting MDSCs through CXCR2 inhibition is an emerging strategy to counteract both mechanisms of resistance." (PMID 34944914, 2021). "Tumor-bearing mouse models exhibited that in vivo treatment using CXCR2 antagonist (SB265610) inhibited tumor growth, and Hepa1-6-shSLC7A2 tumor-bearing mice group was more significant." (PMID 34108444, 2021). "CXCR2 inhibition of PMNs in pancreatic tumors results in increased tumoral T-cell infiltration and depletion of PMNs in tumor bearing mice increases CD8 T-cell activity resulting in an anti-tumor response." (PMID 33986291, 2021).